ADA (adenosine deaminase)
Diseases named in the same sentence as ADA in open-access papers (continued):
Sharing a sentence is not in itself a finding about the gene and the disease.
depression (10 papers, 2018 to 2025). "In MDD, animal model studies have reported that modulating ADA, A1, and/or A2A receptors induces depression-like endophenotypes such as learned helplessness and behavioral despair in rodents." (PMID 40076453, 2025). "About 20 years ago, Elgün and colleagues tested the function of ADA, the enzyme responsible for the conversion of adenosine to inosine, in blood samples of 30 subjects with depression (18 with major and 12 with minor depression)." (PMID 32178222, 2020). "More recently, Herken and colleagues showed that both ADA and XO levels in subjects with major depressive disorder (N = 36) were higher than in healthy controls (N = 20)." (PMID 32178222, 2020). "A decrease in plasma ADA activity in patients with major depression, which correlated negatively with the severity of the illness, suggested that adenosine might be involved in the pathological changes associated with major depression." (PMID 40133606, 2025). "The authors found a reduction of ADA activity, possibly reflecting an impaired immune state in major depressive disorder, with an inverse relationship between enzyme activity and severity of depression." (PMID 32178222, 2020). "To investigate the involvement of NAc RNA editing in alcohol addiction, we generated NAc-specific knockout mice of the double-stranded RNA-specific adenosine deaminase ADAR2 using AAV-GFP/Cre and conducted a battery of behavioral tests including anxiety- and depression-like behaviors." (PMID 30697154, 2018). "Patients with major depression were found to have lower levels of serum adenosine deaminase compared to the control group, with a negative correlation between the enzyme activity and the severity of depression." (PMID 30044406, 2018). "In 1999, Elgun found a decline of adenosine deaminase (ADA) activity in the plasma of patients with major depression, and it had a negative correlation with the severity of depression, which indirectly suggested that adenosine may be involved in the pathological changes of major depression." (PMID 31334608, 2019).
mesothelioma (10 papers, 2012 to 2025). A usually malignant and aggressive neoplasm of the mesothelium which is often associated with exposure to asbestos. "Increased adenosine deaminase acting on dsRNA (ADAR)-dependent editing of Alu elements in the RBM8A 3′UTR was observed in mesothelioma cells compared to mesothelial cells." (PMID 34944051, 2021). "Comprehensive pleural fluid analysis should be performed first, including specific biomarkers such as adenosine deaminase levels, lactate dehydrogenase, cytological examination, and tumor marker assessment, particularly for conditions such as lung adenocarcinoma and mesothelioma." (PMID 41239673, 2025). "Inhibition of adenosine deaminase acting on dsRNA 2 (ADAR2) RNA binding but not ADAR2 editing has shown antitumor effects in mesothelioma." (PMID 40362314, 2025).
metachromatic leukodystrophy (10 papers, 2013 to 2024). A rare lysosomal storage disorder characterized by intralysosomal accumulation of sulfatides in various tissues, leading to progressive deterioration of motor and neurocognitive function. "Phase I/II clinical trials with SIN-lentiviral vectors have been initiated for several PIDs (WAS, ADA-SCID, CGD) as well as for non-PID defects amenable to treatment by gene modified HSCs, including X-linked adrenoleukodystrophy (X-ALD), metachromatic leukodystrophy (MLD) and β-thalassaemia." (PMID 24106209, 2013).
Obesity (10 papers, 2010 to 2024). Accumulation of substantial excess body fat. "An adenosine deaminase polymorphism was shown to be associated with obesity, and adenosine receptor agonists were recommended as therapeutic targets for obesity and dyslipidemia." (PMID 29619754, 2018). "When the obesity causal genes were overlapped with the fasted and fed networks, 7 genes (ADA, BBS5, CBL, CCND3, FASN, FTO and SCARB1) overlapped with PER1's downstream genes in the fed network (Fisher's Exact Test p-value = 0.037)." (PMID 20168994, 2010). "There is a study in the Indian population that links increased ADA activity with being overweight and obesity." (PMID 32984382, 2020). "And in the groups with diet-induced-obesity (OB), both adenosine monophosphate deaminase 2 (Ampd2) and adenosine deaminase (Adat2) were up-regulated." (PMID 26609465, 2015). "Altogether these findings suggest that ADA acting on RNA 1 may contribute to diet-induced obesity by modulating genes related to appetite control, such as ghrelin (“hunger hormone”) and peptide YY (“satiety hormone”)." (PMID 34489711, 2021). "Moreover, it has been recently shown that adenosine, via ADA acting on RNA 1, may control appetite signaling and modulation along with limiting obesity and insulin resistance." (PMID 34489711, 2021). "Furthermore, ADA activity is elevated in T2DM patients and may serve as a marker of inflammation and obesity." (PMID 26284071, 2015).
tuberculous peritonitis (10 papers, 2008 to 2023). A form of peritonitis seen in patients with tuberculosis, characterized by lesion either as a miliary form or as a pelvic mass on the peritoneal surfaces. "This study aimed to investigate the sensitivity and specificity of elevated adenosine deaminase (ADA) levels as a diagnostic marker for tuberculous peritonitis." (PMID 32377284, 2020). "Ascitic tab pale yellow with SAAG 0.9 and positive for adenosine deaminase (66 u/L) sugesstive for tuberculous peritonitis although quantitative PCR and geneXpert for MBT was negative." (PMID 37180328, 2023). "The level of ADA in serum is a useful marker for patients with liver cirrhosis complicated by refractory ascites in order to diagnose tuberculous peritonitis." (PMID 34149447, 2021). "His adenosine deaminase level, a purine-degrading enzyme needed for maturation and differentiation of lymphoid cells, can be used to detect tuberculous peritonitis and in this case was not supportive of TB peritonitis." (PMID 28173830, 2017). "ADA activity of ascitic fluid has been proposed as a highly sensitive (100%) and specific (97%) nonculture method of detecting tuberculous peritonitis especially when using cut-off values from 36 to 40 IU/L." (PMID 24711934, 2014). "Marinez-Vazquez reported that ADA is not specific for tuberculous peritonitis." (PMID 18237424, 2008).
colitis (9 papers, 2009 to 2025). Inflammation of the colon. "In rat models of chronic experimental colitis, administration of two different selective adenosine deaminase inhibitors significantly improved the course of disease." (PMID 33072065, 2020). "Of note, treatment with ADA inhibitor alleviated the severity of inflammation in animals with colitis." (PMID 32849492, 2020). "The inhibition of adenosine deaminase was reported to attenuate mucosal inflammation in experimental colitis through the mechanism of reducing the production of MDA and TNF-α levels." (PMID 32074166, 2020). "An enhanced expression of ADA was also observed in animal models of experimental colitis." (PMID 32849492, 2020). "This altered A3 receptor expression occurred concomitantly with an increase in adenosine deaminase expression in the colonic neuromuscular compartment of rats with colitis, thus decreasing the bioavailability of endogenous adenosine in the A3 receptor microenvironment." (PMID 32849492, 2020). "Besides, the anti-inflammatory actions of adenosine deaminase inhibitors against chronic established colitis depend on the sparing of endogenous adenosine, leading to enhanced adenosine A2A and A3 receptor activation." (PMID 24864134, 2014). "A beneficial effect after inhibition of ADA has been demonstrated in experimental colitis." (PMID 23382912, 2013). "Besides, ADA inhibition could also reduce inflammation in animal models of colitis." (PMID 41360777, 2025). "In a murine model of experimental colitis induced by intrarectal administration of DNBS, the beneficial effect of adenosine deaminase inhibitors was abrogated in the presence of A2AR and A3R antagonists, suggesting a protective role for both receptors." (PMID 33072065, 2020). "Up-regulated genes in both TNBS-colitis and human IBD included ADA, PrPc, and IL-1α, while down-regulated genes consisted of aldehyde dehydrogenase 1 family, member A1 (ALDH1A1), and PPARγ." (PMID 23382912, 2013).
Hepatitis (9 papers, 2013 to 2025). Inflammation of the liver. "Recently, adenosine deaminase (ADA) activity has been introduced as a sensitive and rapid diagnostic marker in evaluation of hepatitis and immunodeficient patients." (PMID 37942194, 2023). "ADA deficiency is also associated with hyperbilirubinemia and hepatitis but can be resolved by ADA replacement therapy." (PMID 24070255, 2013). "Notably, elevated ADA levels have been observed in patients with ICI-related hepatitis, thyroiditis, and encephalitis, indicating activation of the immune response." (PMID 40722787, 2025). "Interestingly, a similar alteration of AdA and AA has been reported in NAFLD and AdA has been reported to promote liver inflammation." (PMID 35493499, 2022). "The hepatitis group logit(P) (HCC group = 1, LC group = 0) was considered the dependent variable, and ADA (X1), AFU (X2), and LAC (X3) were considered the independent variables." (PMID 34557505, 2021). "The hepatitis group logit(P) (LC group = 1, HCC group = 0) was considered the dependent variable, and ADA (X1), AFU (X2), and LAC (X3) were considered the independent variables." (PMID 34557505, 2021). "Therefore, it is unlikely that our ADA-SCID cohort patients had toxic accumulation of metabolites as there are no reports of hepatitis in the first few months of life." (PMID 37208598, 2023).
Insulin resistance (9 papers, 2013 to 2023). Increased resistance towards insulin, that is, diminished effectiveness of insulin in reducing blood glucose levels. "Multiple studies enrolling patients with T2D have found that serum ADA levels are significantly higher in those with T2D than in those without T2D and are associated with poor glycemic control and insulin resistance." (PMID 34319903, 2021). "ADA was described as an important modulator of glucose metabolism in different tissues and its increased activity may be a direct cause of insulin resistance." (PMID 33053898, 2020). "Hence, if ADA activity is inhibited, insulin sensitivity may be improved, and processes associated with the pathophysiology of insulin resistance such as cellular proliferation, inflammation, and T-cell activity can also be affected." (PMID 33053898, 2020). "Increased activity of ADA can directly contribute to insulin resistance, which in turn impairs neurotrophic signaling and mitochondrial dysfunction, ultimately leading to nerve dysfunction and neuropathy." (PMID 36267565, 2022). "Adenosine, a substrate of ADA, can promote glucose uptake into cells, while high levels of ADA can inhibit glucose uptake into cells by degrading adenosine, thereby aggravating insulin resistance." (PMID 34319903, 2021). "Serum adenosine deaminase (ADA) is an important enzyme that regulates the biological activity of insulin, and its levels are greatly increased in inflammatory diseases with insulin resistance." (PMID 34001220, 2021). "Next to the key role of ADA in T-cell activity and insulin resistance, it is bound on the cell surface by CD26 protein (DPP-4) that is an important modulator of insulin secretion." (PMID 33053898, 2020). "Further, metformin, which decreases insulin resistance also lowers ADA levels, thereby establishing positive correlation between ADA and insulin resistance." (PMID 24453844, 2013). "Adenosine is involved in insulin mediated glucose uptake in skeletal muscle and high ADA activity tends to decrease glucose uptake into cells and thus contributes to insulin resistance." (PMID 24453844, 2013). "Further, Gowda and his colleagues found that patients with T2D who received metformin treatment might have reduced serum ADA levels through improved insulin resistance." (PMID 34319903, 2021). "Thus, recent evidence suggests that ADA might have a role in insulin signaling and could serve as a marker for insulin resistance in T2DM39." (PMID 38092892, 2023). "Garlic also showed antihypertensive activity as well as an inhibitory effect on adenosine deaminase (ADA) activity, an enzyme possibly involved in insulin resistance." (PMID 34567218, 2021). "As ADA has been putatively associated with inflammation, and adipose tissue inflammation is the hallmark of insulin resistance in obese T2DM patients, the serum level of ADA in nonobese T2DM is ill-defined." (PMID 24453844, 2013). "This study intends to evaluate the serum level of ADA in the pathogenesis of insulin resistance in nonobese T2DM patients." (PMID 24453844, 2013).
sarcoidosis (9 papers, 2015 to 2025). Sarcoidosis is a multisystemic disorder of unknown cause characterized by the formation of immune granulomas in involved organs. "We aimed to investigate the diagnostic features of YKL-40, sIL-2R, ACE, hs-CRP, neopterin concentrations and ADA markers in active and inactive discrimination of sarcoidosis disease." (PMID 30154391, 2018). "Serum ADA activity has been shown to be increased in sarcoidosis, especially in untreated patients and it has been suggested that ADA assay may be useful as a marker of the activity of the disease." (PMID 30154391, 2018). "This case highlights several key aspects as follows: sarcoidosis should be considered in the differential diagnosis of exudative lymphocytic pleural effusion with elevated ADA, particularly when microbiological tests are negative." (PMID 41328078, 2025). "Although various markers, such as adenosine deaminase (ADA) activity, serum amyloid A (SAA) levels, and sIL-2r levels, have been used in adults to support diagnosis and monitor disease activity, none of these markers have been studied widely in children with sarcoidosis." (PMID 37108489, 2023). "Sarcoidosis patients in the active phase of the disease were significantly higher YKL-40, sIL-2R, ACE and hs-CRP levels than those in the inactive phase, while ADA activities and neopterin levels did not display any significant difference between the active and inactive disease groups." (PMID 30154391, 2018). "Sarcoidosis patients in the active phase of the disease were significantly higher YKL-40, sIL-2R, hs-CRP levels and ACE activity than those in the inactive phase, while ADA activities and neopterin levels did not display any significant difference between the active and inactive disease groups." (PMID 30154391, 2018).
systemic lupus erythematosus (9 papers, 2012 to 2024). An autoimmune multi-organ disease typically associated with vasculopathy and autoantibody production. "In some lupus patients, there is increased adenosine deaminase activity (and presumably lower adenosine content) in blood." (PMID 29942314, 2018). "Now that our study has highlighted the potential importance of purinergic signaling in lupus, future studies should consider parallel/compensatory pathways such as CD38/CD203a, as well as adenosine deaminase, in both mice and humans." (PMID 29942314, 2018). "Furthermore, in cases of Behcet's illness, juvenile idiopathic arthritis, and systemic lupus erythematosus (SLE), ADA has been proposed as an alternate measure of disease activity." (PMID 38699124, 2024).
bacterial meningitis (8 papers, 2014 to 2024). Inflammation of the membranes surrounding the brain and spinal cord due to a bacterial infection. "In multivariate analysis, we found that rural residence and raised ADA (10 IU/L) were independently associated with bacterial meningitis as compared with viral meningitis." (PMID 34020719, 2021). "Age 40 years, rural residence, raised CRP, and all parameters in CSF analysis (raised WBC count, neutrophil count, protein, and ADA; and low CSF/blood glucose ratio) were associated with bacterial meningitis in the univariate analysis." (PMID 34020719, 2021). "We found that CSF ADA (10 IU/L) was strongly associated with bacterial meningitis and TBM when compared with viral meningitis." (PMID 34020719, 2021). "CSF ADA 10 IU/L was strongly associated with bacterial meningitis and TBM." (PMID 34020719, 2021). "Individually all CSF ADA results in the ‘Confirmed cryptococcal meningitis’, ‘Confirmed bacterial meningitis’, ‘Confirmed viral meningitis/encephalitis’ and ‘Confirmed ventriculitis’ categories were compared with the ‘Confirmed TBM’ category." (PMID 28143441, 2017). "Systematic review and meta-analysis have shown that CSF ADA cannot differentiate TBM from bacterial meningitis; however, it can improve the diagnosis of TBM at ADA level >8 IU/L, particularly when bacterial infection has been ruled out." (PMID 34020719, 2021). "The measurement of an enzyme called adenosine deaminase (ADA) has been used to detect TBM; although sensitive, ADA has been found to be involved in the pathology of other infections such as bacterial meningitis and ventriculitis, making measurement of ADA an unreliable way of diagnosing TBM." (PMID 39689104, 2024).
Cirrhosis (8 papers, 2014 to 2025). A chronic disorder of the liver in which liver tissue becomes scarred and is partially replaced by regenerative nodules and fibrotic tissue resulting in loss of liver function. "ADA has been investigated as a rapid diagnostic tool for TBP, however, the role of ADA in the setting of cirrhosis is controversial." (PMID 24669272, 2014). "ADA level above 30 U/L is known to be 94% sensitive in diagnosis of peritoneal tuberculosis; however, the sensitivity is much lower in patients with cirrhosis." (PMID 24715911, 2014). "Adenosine deaminase level in ascitic fluid is also a potentially useful marker which can assist with the diagnosis of TB in the peritoneum, although it can also be elevated in cirrhosis." (PMID 41244976, 2025). "This co-morbidity of cirrhosis and peritoneal TB may explain the high level of ADA in our study population." (PMID 32197582, 2020). "Furthermore, this work provides novel evidence for an association between plasma ADA levels and MASH, as increased ADA activity had previously been described only in T2DM, acute hepatitis, and cirrhosis." (PMID 41303424, 2025). "Adenosine deaminase (ADA) can be a useful lab to include given that its sensitivity approaches 58% with specificity 95% in patients without cirrhosis." (PMID 37124145, 2023).
tuberculous pericarditis (8 papers, 2013 to 2025). "If tuberculous pericarditis is suspected, then performing polymerase chain reaction and adenosine deaminase activity assays on fluid increase the diagnostic yield." (PMID 29397796, 2018). "In pericardial tuberculosis, the sensitivity and specificity of ADA levels 40 U/L are approximately 88 and 83%, respectively." (PMID 28702302, 2016). "Elevated pericardial adenosine deaminase (ADA) activity and increased interferon-γ (IFN- γ) levels in pericardial fluid are also highly suggestive of tuberculous pericarditis, and are less time-consuming when compared to culture, but more costly." (PMID 36158349, 2022).
X-linked adrenoleukodystrophy (8 papers, 2011 to 2024). X-linked adrenoleukodystrophy (X-ALD) is a peroxisomal disorder resulting in cerebral demyelination, axonal dysfunction in the spinal cord leading to spastic paraplegia, adrenal insufficiency and in some cases testicular insufficiency. "Gamma retroviral and lentiviral vectors have performed well for ex vivo gene therapy of hematopoietic stem cells for treatment of X-SCID, ADA-SCID and X-linked Adrenoleukodystrophy." (PMID 21774770, 2011).